KMT2D (lysine methyltransferase 2D)
Diseases named in the same sentence as KMT2D in open-access papers (continued):
Sharing a sentence is not in itself a finding about the gene and the disease.
tumor (continued). "KMT2D functions as a bona fide tumor suppressor across cancers." (PMID 39564571, 2024). "Consistent with the results in SCC23 cells, although the in vitro proliferation rates of SCC1 cells were not affected by the loss of KMT2D, knockout of KMT2D significantly increased the subcutaneous tumor formation." (PMID 39117659, 2024). "Moreover, KMT2D exerts a tumor-suppressive role and acts as a bridge in mediating the antitumor effect of vitamin C in HCC." (PMID 39564571, 2024). "In contrast, KMT2D appeared as a weak tumor-suppressor gene." (PMID 38786098, 2024). "Using KMT2D loss-of-function (KMT2DLOF) mutations as a model, we illustrate the utility of in silico genetic networks in uncovering novel functional associations and vulnerabilities in cancer cells with LOF alterations affecting tumour suppressor genes." (PMID 39578878, 2024). "Moreover, KMT2D functions as a tumor suppressor and mediates a general antitumor effect of TET2 agonist vitamin C in HCC." (PMID 39564571, 2024). "Considering KMT2D’s role in the PI3K/AKT/SOX2 axis in NSCLC, which affects tumor growth, combined targeted therapy of KMT2D and PI3K may offer new treatment possibilities for LSCC." (PMID 39544292, 2024). "In mouse xenograft model, knockdown of either KMT2D or YBX1 inhibited tumour growth." (PMID 38967349, 2024). "The mutations in the chromatin modifier genes KDM6A and KMT2D displayed low AFs (0.02, 0.01, respectively), suggesting minimal impact on tumor biology especially as they were not carried into the metastatic lesions." (PMID 39349591, 2024). "With similar findings for other cancer types, KMT2D is known as a tumor suppressor." (PMID 39765675, 2024). "In addition, we identified mutations in epigenetic regulation genes, such as KMT2D, KMT2E, SMYD3, ASH1L, KMT2C, and KMD4B, in the tumor clones." (PMID 38010945, 2024). "Given the frequent, seemly loss‐of‐function mutations of KMT2D in AML and its tumor suppression capacity in other cancers, we hypothesized KMT2D is a tumor suppressor in AML." (PMID 37142882, 2023). "Our data identify a direct biochemical and functional interaction between CREBBP and KMT2D in the GC, with implications for their role as tumor suppressors in FL/DLBCL and for the development of precision medicine approaches targeting enhancer defects induced by their combined loss." (PMID 36893259, 2023). "And KMT2D was reported as a potential tumor suppressor in other type of cancers." (PMID 37831226, 2023). "Here, we demonstrate that tumor cell ablation of mixed-lineage leukemia 3 and 4 (MLL3 and MLL4, also known as KMT2C and KMT2D, respectively), two enhancer-associated histone H3 lysine 4 (H3K4) mono-methyltransferases, increases tumor immunogenicity and promotes anti-tumor T cell response." (PMID 36323669, 2022). "KMT2D plays a major role in enhancer regulation in mammalian cells, and thus contributes to many important processes such as development, differentiation, metabolism and tumour suppression." (PMID 35073341, 2022). "It has been found that KMT2D is closely related to tumor cell migration and adhesion." (PMID 35281840, 2022). "Previous reports demonstrated that the KMT2D gene acts as a tumor suppressor in various cancers." (PMID 34553842, 2022). "Nonetheless, the role of KMT2D in tumor development remains largely controversial." (PMID 35477537, 2022).
tumor (continued). "Furthermore, KMT2 family genes, such as KMT2A, KMT2C, and KMT2D, were frequently mutated in TMB‐H or PD‐L1+ tumor samples." (PMID 33655698, 2021). "Our study offers new insight into the functional mechanism of the KMT2D protein in tumor survival." (PMID 34758724, 2021). "Additionally, KMT2D expression and alterations in tumor tissue and normal urothelium were assessed at a single time point in samples obtained from RNU." (PMID 34834500, 2021). "We also found evidence of tumor suppressor effects, such as negative enrichment for genes down regulated in Kmt2d or Tet2 deficient GCs." (PMID 34621263, 2021). "Previous results indicate that the KMT2D protein promotes tumorigenesis via dysregulation of enhancer activity, disrupting normal developmental processes and altering gene networks regulated by tumor suppressors or oncoproteins." (PMID 34758724, 2021). "The expression of KMT2D in tumor was lower than that in normal tissues in the GSE53625." (PMID 35127817, 2021). "Interestingly, KMT2D activates expression of the tumor suppressor Per2 and thereby downregulates expression of tumor-promoting glycolytic genes in K-RasG12D–driven lung tumors." (PMID 34194626, 2021). "KMT2D plays a critical role in epigenetic regulation and may have an impact on development, differentiation, metabolism and tumor suppression." (PMID 34885165, 2021). "Therefore, KMT2D plays a critical role in activating tumor-suppressive enhancers and super-enhancers." (PMID 34194626, 2021). "Recently, Maitituoheti at al. identified KMT2D serving tumor suppressor roles in CM." (PMID 34575678, 2021). "Although tumors derived from Smc3 haploinsufficient B cells display a Kmt2d loss of function-like transcriptional profile, we did not detect consistent downregulation of Kmt2d mRNA itself in tumor cells." (PMID 34621263, 2021). "For LG tumor samples, the nuclear expression of KMT2D was low in pTa but increased with stage." (PMID 34834500, 2021). "Additionally, in one case we found, for the first time, integration involving the tumor suppressor gene KMT2D, adding to previous reports of rare MCPyV integration into host tumor suppressor genes in MCC." (PMID 32878339, 2020). "No genes were found to be recurrently mutated, however, two tumours had mutations in histone methytransferases (SETD2 and KMT2D) and one also had a mutation in a demethylase (KDM4A), all previously associated with neoplasia and all mutations predicted to be deleterious." (PMID 32698852, 2020). "Among ERGs that could be classified as tumor suppressors, KMT2D, KMT2C, ARID1A, ATRX, CREBBP, and PBRM1 were frequently mutated in many cancer types, whereas oncogenic ERGs were each mutated in specific cancer types, mainly IDH1 in LGG and DNMT3A in LAML." (PMID 32963031, 2020). "Of note, truncating mutations in KDM6A, KMT2D, and KMT2C were frequently observed (74%; 14/19), suggesting that disruption of the epigenetic regulatory pathway may be involved in tumor development in urothelial BC." (PMID 32984035, 2020). "As the presence of KMT2D and SETD2 mutations were consistent in TNBC, we next explored if KMT2D and SETD2 mutational signatures were associated with detrimental prognosis in this specific tumor subtype." (PMID 30990809, 2019). "Interestingly, mouse models of Crebbp and Kmt2d deletion show a more pronounced tumor-promoting phenotype when Cre-mediated knockout is induced prior to the GC44–48." (PMID 31586074, 2019).
tumor (continued). "Our comparison of the mRNA and miRNA expression profiles of mutated and wild‐type KMT2D suggested that two signaling pathways (FOX1–miR‐1224‐5p–DLK1 and HIF/GATA5–miR‐133a‐3p–DRD5) may mediate the tumor suppressive effect of the KMT2D mutation." (PMID 30984543, 2019). "In B-lymphoma cells, the mutation or knockdown of KMT2D inhibited methylation of lysine 4 on histone H3 (H3K4), downregulated FBXW7 expression, activated NOTCH signaling pathway and downstream MYC/TGF-β1, resulting in alterations of tumor-induced regulatory T cell trafficking." (PMID 39113693, 2024). "Moreover, KMT2D plays a role in addressing tumor resistance." (PMID 39620228, 2024). "Moreover, the KMT2D-dependent instruction of the tumor microenvironment might be relevant in PDAC, suggesting that epigenetic therapies can tune the tumor cell-intrinsic to -extrinsic rheostat." (PMID 37659057, 2023). "To further investigate the relationship between KIRP tumor immunity, we performed the correlation analysis between KIRP immune checkpoint genes (CTLA4, HAVCR2, PDCD1, PDCD1LG2, and TIGIT) and high mutation frequency genes (TTN, MET, KMT2C, PKHD1, SETD2, and KMT2D)." (PMID 36618928, 2022). "immunohistochemical detected additional non-KMT2D-mutated aGCTs with loss of nuclear KMT2D expression, suggested that nongenetic KMT2D inactivation might occur in this tumor type." (PMID 35356927, 2022). "Further experiments on several OSCC cell lines, in which KMT2D functions as a regulator of H3K4me1 and H3K27ac levels, also confirmed that the expression of KMT2D contributed to the stem-like properties, metastatic potential, and in vivo tumor growth ability of OSCC cells." (PMID 35477537, 2022). "In addition to KMT2D, the authors identified seven more epigenetic regulators in CM cell lines (KDM1A, APOBEC2, HDAC6, KMT2F, SETD4, KAT4, and KDM5B) whose loss accelerates CM tumor progression." (PMID 34575678, 2021). "Therefore, in future studies, it would be interesting to determine whether KMT2D regulates oncogenic factors or tumor suppressors via methylation." (PMID 34194626, 2021). "KMT2C and KMT2D proteins restrain cell proliferation and could be considered tumor suppressors." (PMID 34572812, 2021). "Therefore, KMT2D-mediated Per2 activation represents a previously unknown tumor-suppressive mechanism that links an epigenetic tumor suppressor to a circadian rhythm regulator with direct metabolic implications." (PMID 35071240, 2021). "However, whether other structures of KMT2D protein are vital for gene transcription in tumor cells remains unclear, and the mechanism remains to be comprehensively determined." (PMID 34758724, 2021).
tumor (continued). "IHC detects additional non-KMT2D-mutated aGCTs with loss of nuclear KMT2D expression, suggesting that non-genetic KMT2D inactivation may occur in this tumor type." (PMID 29950560, 2018). "Histone lysine methyltransferase 2D (KMT2D) enhances the stability of the WDR5 protein via LLPS, facilitates the formation of the KMT2D‐enzyme complex, and catalyses the monomethylation of H3K4 to stimulate tumour growth." (PMID 40211955, 2025). "In SCCs, TERT, PIK3CA, and matrix metalloproteinases (MMPs) are common oncogenes, whereas KMT2D and CDKN2A are common tumor suppressors." (PMID 39455281, 2025). "Histone-lysine N-methyltransferase 2D (KMT2D) is an H3K4 methyltransferase and a potential tumor suppressor with a crucial role in regulating gene expression." (PMID 41341998, 2025). "We found that Kmt2d-HT mice showed significantly increased tumor lesion areas, SCC numbers, SCC areas, and tumor invasion grades as well as Ki-67 positive tumor cell numbers compared with Kmt2d-WT mice, indicating that heterozygous deletion of Kmt2d could accelerate HNSCC progression." (PMID 39117659, 2024). "While KMT2D is oncogenic, its subunit, UTX, can function as a tumor suppressor, reducing epithelial-to-mesenchymal transition (EMT)." (PMID 38347590, 2024). "To further investigate the role of KMT2D as a tumor suppressor in human HNSCC, we generated KMT2D knockout (KMT2D-KO) SCC23 HNSCC cells by CRISPR-Cas9 mediated gene editing." (PMID 39117659, 2024). "Through IHC staining, we found that KMT2D was significantly downregulated in PDAC tissues, and negatively correlated with tumor stage, lymph node metastasis, and distal metastasis in PDAC patients." (PMID 38015024, 2024). "Studies have demonstrated that KMT2D modulates SOX2 expression in NSCLC through a PI3K-dependent manner, significantly impacting tumor growth." (PMID 39544292, 2024). "Novel targets such as nuclear receptor-binding SET domain protein 3 (NSD3), lysine methyltransferase 2 D (KMT2D), and ubiquitin-specific peptidase 28 (USP28), are related to tumor microenvironment (TME) and immune cells." (PMID 39544292, 2024). "However, even an in vitro or in vivo oncogenic effect of KMT2D perturbation might not directly translate to a clinical relevant tumor predisposition." (PMID 35856126, 2023). "Inactivation of many genes that were functional tumor suppressors in KRAS-driven lung tumors, including Lkb1, Setd2, and Kmt2d, were deleterious in EGFR-driven lung tumors." (PMID 37828026, 2023). "From this study, proteins of interest identified by tandem MS-MS that were decreased in sera from tumor-bearing rats treated with OKN-007, compared to untreated, included ABCA2, ATP5B, CNTN2, ITGA3, KMT2D, MYCBP2, NOTCH3, and VCAN." (PMID 35053843, 2022). "In the present study, we found that the expression of KMT2D was elevated in OSCC compared to paracancerous specimens and was correlated with a more advanced tumor grade." (PMID 35477537, 2022). "Proteins of interest identified by tandem MS-MS that were decreased in sera from tumor-bearing rats that were either OKN-007-treated or untreated included ABCA2, ATP5B, CNTN2, ITGA3, KMT2D, MYCBP2, NOTCH3, and VCAN." (PMID 35053843, 2022). "To further confirm the role of KMT2D in the development of OSCC, we analyzed the staining intensity (i.e., histoscores) of KMT2D in OSCC specimens diagnosed with different tumor grades." (PMID 35477537, 2022). "Epigenetic alterations relating to histone methylation (KMT2D, KMT2C, EZH2), histone acetylation (CREBBP, EP300), and DNA methylation (TET2) play an important role in tumor progression for FL and DLBCL." (PMID 36497332, 2022).
tumor (continued). "Here, we will focus on the mutations of the histone acetyltransferase CREBBP and the methyltransferases KMT2D and EZH2 that play a key role in the FL microenvironment, and have detrimental consequences on the anti-tumor immune response." (PMID 35022084, 2022). "In in vitro and in vivo models, knockdown of KMT2D reduced the colony formation, migration and invasion abilities of OSCC cells and delayed tumor growth." (PMID 35477537, 2022). "To summarize, our findings indicate that KMT2A, KMT2C, KMT2D, and KMT2H are more likely to inhibit tumor occurrence, whereas other KMT2s are more likely to promote tumor occurrence and are generally associated with poor prognosis." (PMID 35058979, 2022). "In this review, first we describe the most frequent epigenomic alterations in FL (KMT2D, CREBBP and EZH2) that affect the immunological niche, and their potential consequences on the informational transfer between tumor B cells and their microenvironment." (PMID 35022084, 2022). "Here, we show that the KMT2D protein contains two typical LCD structures that are key to the increased proliferation and migration of tumor cells." (PMID 34758724, 2021). "A different methyltransferase, known as histone-lysine N-methyltransferase 2D (KMT2D), might play a role in deregulating genes which are critical for cell migration and actively participate in melanomagenesis, as shown in a study using patient derived tumor samples." (PMID 34440824, 2021). "We found the co-occurrence of genetic mutations in tumors with PARP1 alterations to be involved with some genes such as KMT2D/2C as driver genes, PIK3CA, ARID1A, H3F3A, HIST3H3, RYR2, and thus, PARP1 alteration should promote tumor mutability." (PMID 34531868, 2021). "Low levels of KMT2D induce carcinogenesis via epigenetic modifications, repressing the expression of Period Circadian Regulator 2 (PER2) gene, which regulates tumor-promoting glycolytic genes." (PMID 33602320, 2021). "Additional tumor suppressors such as NOTCH family genes and KMT2D are inactivated at lower rates in MCPyV-negative MCC." (PMID 32878339, 2020). "Inhibiting PI3K affects tumor growth in estrogen receptor (ER)-positive breast cancer and activates glucocorticoid-regulated kinase 1 through KMT2D, regulating ER-dependent transcription via a negative feedback loop." (PMID 39544292, 2024). "In addition, KMT2D and YBX1 were significantly overexpressed in the tumour tissues of patients with advanced TNM stage and recurrence." (PMID 38967349, 2024). "Given the lack of WRN inhibitor response data in cancer patients harbouring KMT2DWT and KMT2DLOF tumours, the lack of a relationship between KMT2D status and WRN inhibitors in patient samples (e.g. biopsies) remains a limitation of our study." (PMID 39578878, 2024). "Additionally, KMT2D overexpression can also epigenetically activate PI3K/Akt and upregulate EMT and oncogenic pathways, promoting tumor radioresistance." (PMID 37455903, 2023). "The results showed that knockdown of KMT2D gave rise to delayed growth dynamics of SCC4-derived xenografts, as confirmed by the decreased tumor volume and weight of xenografts initiated by SCC4 cells transfected with Sh-KMT2D, which were recorded at each observation time point." (PMID 35477537, 2022). "However, the genes such as KMT2D, DNAH11, and BRAF, which have a positive correlation with tumor immunity level, also up-regulated several immune-related miRNAs." (PMID 34211853, 2021). "A total of 19 tumor specimens (37.3%) showed negative KMT2D expression, whereas 32 tumor specimens showed positive KMT2D expression (62.7%)." (PMID 34834500, 2021).